RGS16 (regulator of G protein signaling 16)
Diseases named in the same sentence as RGS16 in open-access papers (continued):
Sharing a sentence is not in itself a finding about the gene and the disease.
tumor (continued). "In our eight mRNAsi based signature, high expression of RGS16, LYVE1, hnRNPC, ANP32A, and AIMP1 are correlated with a high risk of death as these genes focus in promoting cell proliferation and tumor progression, similar to stem cells." (PMID 33329703, 2020). "We took advantage of the histocompatibility of this cell line and regulator of G protein 16 (RGS16) knock out mice to test the impact of RGS16 on the tumor growth." (PMID 30526524, 2018). "The difference in tumor weight between WT and RGS16 KO mice was statistically significant (p < 0.05) in spite of high individual variability." (PMID 30526524, 2018). "Strikingly, RGS16 expressed by the recipient mouse controlled tumor development since larger primary tumors developed in RGS16 KO mice compared to WT." (PMID 30526524, 2018). "As in humans, tumor heterogeneity exists between mice, reflected by differences in Rgs16::GFP expression levels, histology, immunofluorescence and response to treatment in KIC mice." (PMID 26438693, 2015). "A three-dimensional rotational movie shows Rgs16::GFP expression in a PDA tumor, several small areas of neoplasia and normal acinar cells in lobes at the head of the pancreas." (PMID 26438693, 2015). "The Rgs16::GFP transgene is a KrasG12D-dependent marker of all stages of PDA neoplasia and its expression increases proportionally to tumor burden in KIC mice – a genetically engineered mouse model of PDA." (PMID 26438693, 2015). "Here, we show that the Rgs16::GFP transgene is a KrasG12D-dependent marker of all stages of neoplasia in KIC mice – IPMN, PanIN and PDA." (PMID 26438693, 2015). "DUSP6 and RGS16 (regulator of G-protein signaling 16) transcriptional upregulation inhibits tumor cell proliferation and ERK phosphorylation and serves as a negative regulatory mechanism to prevent further ERK phosphorylation." (PMID 19636436, 2009). "Our data therefore indicates that RA-induced upregulation of DUSP6 and RGS16 inhibits tumour cell proliferation, through acting on two levels of RAS-RAF-MEK-ERK signalling pathway and eventually synergistically reducing ERK phosphorylation." (PMID 16012519, 2005). "DUSP6 and RGS16 transcriptional upregulation inhibits tumour cell proliferation and ERK phosphorylation, and serves as a negative regulatory mechanism to prevent further ERK phosphorylation." (PMID 16012519, 2005). "After RGS16 knockdown, the tumor weights and sizes were lower than those of the control group." (PMID 40413527, 2025). "Consequently, our findings provide compelling evidence suggesting that RGS16 fosters tumor growth by impeding tumor cell apoptosis in an in vivo setting." (PMID 38906869, 2024). "The stimulatory role of RGS16 in regulating the viability of CRC cells suggests that RGS16 may serve as an oncogene driving tumor progression." (PMID 38906869, 2024). "Notably, RGS16 emerged as the unique family member with high expression in tumor tissue, holding predictive significance for both OS and PFS." (PMID 38906869, 2024). "Studies have shown that G protein signaling 16 (RGS16) can act as a tumor suppressor by inhibiting the growth of PI3K dependent breast epithelial cells, while inhibiting PI3K/AKT downregulates REST expression and induces NE markers in LNCaP, PC3 and LNCaP95 cells." (PMID 36686485, 2022). "Above all, RGS16 protein exerts a critically influential regulatory effect in these malignancies through GPCRs and other non-classical signaling pathways, and has the to be a potential therapeutic target for the regulation of tumor processes." (PMID 36120550, 2022). "The expression level of RGS16 was significantly related with higher tumor grade (P=0.015)." (PMID 33747931, 2021). "Thus, Rgs16 expression can be effectively used to follow tumor progression in the mouse models of PDA therapy and identify potential new therapeutics." (PMID 33244070, 2020). "At later times in tumor progression, Rgs16::GFP expression is restricted to neoplasia in PDA." (PMID 33244070, 2020).
tumor (continued). "Thus, RGS16 is involved in the immune response against tumors, possibly by affecting immune cell activation and infiltration into the site of the tumor or influencing the local milieu in the tissue." (PMID 30526524, 2018). "Importantly, we observed that the decrease in tumor growth induced by the overexpression of ORF3 was still observed in RGS16 KO mice, demonstrating that an RGS16 expression around the tumor is not required for ORF3 antitumoral activity." (PMID 30526524, 2018). "Thus, Rgs16::GFP reports the precise region of activated KrasG12D signaling at tumor initiation and throughout progression." (PMID 26438693, 2015). "Similarly, the tumor-promoting role of RGS16 was substantiated in vivo." (PMID 40413527, 2025). "The Ki67 labeling of tumor tissue depicted a positive correlation between RGS16 and tumor cell proliferation activity, whereas the Tunel assay and immunohistochemistry staining of cleaved caspase 3 exhibited negative association between RGS16 and apoptosis levels in tumor cells." (PMID 38906869, 2024). "However, the tumor development started at the same time both in WT and RGS16 KO mice." (PMID 30526524, 2018). "IHC staining showed that after RGS16 was downregulated, the expression levels of Ki67 and RGS16 showed a decline, and the GPX4 protein in tumor tissues was also reduced." (PMID 40413527, 2025). "Further exploration in TCGA databases unveiled a correlation between RGS16 expression and the extent of TNM stage classification (stage I–stage IV) as well as initial tumor invasion (T1–T4)." (PMID 38906869, 2024). "The mRNA expression levels of RGS16, SNAI1, CDR2L, FRMD5, and FSTL3 were higher in tumor samples than that in adjacent normal tissues in TCGA-COAD cohort, suggesting that these five key genes participate in the progression of CC." (PMID 36925652, 2023). "RGS16-GFP has recently been reported in caerulein-induced acinar cell dedifferentiation, early tumor and throughout PDA progression." (PMID 36120550, 2022). "According to the data in TCGA tumor samples, the copy numbers of DHX37 were positively correlated with TIM3, LAG3 and NCOR2, while they were negatively correlated with PD-L1, RGS16 and TOX." (PMID 33490273, 2021). "A histone deacetylase inhibitor, TSA, stimulated Rgs16::GFP expression in PDA primary cells, potentiated gemcitabine and JQ1 cytotoxicity in cell culture, and Gem + TSA + JQ1 inhibited tumor initiation and progression in vivo." (PMID 33244070, 2020). "The validation step in Rgs16::GFP mice is quantitative, cost effective, and rapid—10 min per mouse to quantitate tumor burden following a 2 week in vivo assay prior to weaning in a spontaneous model of PDA in transgenic mice." (PMID 33244070, 2020). "Rgs16::GFP is expressed in response to caerulein-induced acinar cell dedifferentiation, early neoplasia, and throughout PDA progression." (PMID 33244070, 2020). "In this prognostic signatures, high expression of RGS16, LYVE1, hnRNPC, ANP32A, and AIMP1 focus in promoting cell proliferation and tumor progression." (PMID 33329703, 2020). "In KIC;Rgs16::GFP mice, GFP is induced in the earliest pancreatic lesions and in a subset of PDA cells throughout tumor progression." (PMID 33244070, 2020). "These seem to be specialized responses in which Rgs16 and CPA1 expression is secondary to PDA tumor growth." (PMID 26438693, 2015). "We crossed Rgs16::GFP bacterial artificial chromosome (BAC) transgenic mice with KIC mice and show that the Rgs16::GFP transgene is a KrasG12D-dependent marker of all stages of PDA, and increases proportionally to tumor burden in KIC mice." (PMID 26438693, 2015). "These are specialized responses in which Rgs16 and CPA1 expression is secondary to PDA tumor growth." (PMID 26438693, 2015). "We showed that a standard-of-care combination of gemcitabine+Abraxane (GA) reduced initiation of neoplasia in KIC;Rgs16::GFP reporter mice." (PMID 26438693, 2015).
tumor (continued). "The distribution and intensity of Rgs16::GFP expression is proportional to and coincident with tumor burden." (PMID 26438693, 2015). "To accelerate the discovery of effective drugs that inhibit PDA in vivo, we developed Rgs16::GFP as a sensitive reporter of PanIN and PDA initiation, progression and tumor size by 4 weeks of age (P29) in KIC mice." (PMID 26438693, 2015). "Consequently, further elucidation is warranted to determine the specific functions of RGS16 in CRC, including its impact on tumor staging and its biological role within CRC cells." (PMID 38906869, 2024). "The results demonstrated that RGS16, SNAI1, CDR2L, FRMD5, and FSTL3 consistently exhibited significantly higher relative mRNA expression levels in CC tumor samples than in paired adjacent normal tissues." (PMID 36925652, 2023). "While the control of autologous tumor growth was impaired in RGS16 KO mice, our data suggest that the effect of ORF3 does not implicate RGS16." (PMID 30526524, 2018). "Widespread, high Rgs16::GFP expression in acinar-like cells (co-expressing high CPA1) was sometimes observed in peripheral lobes with edema that sit beyond (proximal to) tumor nodules in KIC pancreata." (PMID 26438693, 2015). "PDAs in KIC mice have intense Rgs16::GFP expression but little or no AB/PAS staining, whereas Rgs16::GFP is significantly lower in regions of neoplasia that are AB/PAS-positive (inserts)." (PMID 26438693, 2015). "In a proof-of-principle for drug screens, we find that weanling KIC mice with PDA treated with the standard-of-care combination of gemcitabine and nab-paclitaxel (Abraxane) for 2 weeks have significantly lower Rgs16::GFP expression, and reduced tumor size and occurrence." (PMID 26438693, 2015). "In addition, we investigated that the expression of DHX37 was correlated with several tumor-related immune genes (PD-L1, TIM3, LAG3, TOX, RGS16, and NCOR2), indicating that it may play crucial roles in tumor immune dysregulation." (PMID 33490273, 2021). "Rgs16::GFP marks the earliest lesions, is proportional to and coincident with early tumor burden, and is expressed throughout PDA progression; importantly, Rgs16::GFP is not expressed in pancreas of healthy adult mice." (PMID 33244070, 2020). "Images of the five brightest non-overlapping fields of Rgs16::GFP expression were then collected, representing the regions of greatest tumor burden." (PMID 26438693, 2015). "An important point is that, although all pancreatic cells in KIC mice express KrasG12D and have inactivated Cdkn2a (indeed, p48::Cre drove TdTomato expression throughout the pancreas), Rgs16::GFP is absent at P15 except for expression in the earliest lesions, and then throughout tumor progression." (PMID 26438693, 2015). "However, 13-cis-RA did not significantly modulate RET, RGS16, FLNB, and EGR1 expression in the tissue samples from tumour-bearing animals treated for 5 days." (PMID 16012519, 2005).
cancer (18 papers, 2008 to 2025). A tumor composed of atypical neoplastic, often pleomorphic cells that invade other tissues. "G-protein signaling regulator 16 (RGS16) has been confirmed that RGS16 is associated with cancer, neurodegenerative diseases, and cardiovascular diseases." (PMID 38363937, 2024). "To extend this analysis, we surveyed Rgs16 expression compared to Kras oncogenic allele status in bulk RNAseq obtained from established cancer cell lines from human PDA and a variety of other human cancer cell lines, and human PDA tumors (TCGA)." (PMID 33244070, 2020). "RGS16 was of interest to our study for two reasons: 1) RGS16 regulates GPCRs, which are common targets for deregulation in cancer and 2) RGS16 has been linked to regulating the MAPK/RAS, PI3K/AKT, RhoA, and SDF-1/CxCR4 oncogene pathways." (PMID 25568667, 2014). "Regulator of G-protein signaling 16 (RGS16) has been found to be correlated with the malignant progression of various cancers, and BHLHE40 is highly expressed in GC." (PMID 40413527, 2025). "The capacity for Rgs16 induction was probably lost in human cancer cell lines that were passaged innumerable times." (PMID 33244070, 2020). "Immunofluorescence analysis of KIC;Rgs16::GFP tumors show GFP is co-expressed with Sox9 positive cancer cells." (PMID 33244070, 2020). "Primary cancer cells isolated from KIC-Rgs16::GFP mice were sorted for high and low expression of Rgs16::GFP (2.6-fold differential expression following 12 h incubation in 50% or 5% FBS, respectively)." (PMID 33244070, 2020). "The current data suggests RGS16 plays a role in cancer signaling, however, more research is needed to delineate the function of RGS16 in cancer cells." (PMID 25568667, 2014). "RGS16 has been implicated in negatively regulating the MAPK, AKT/PI3K, RhoA, and SDF-1/CXCR4 oncogene pathways in normal or cancer cell lines." (PMID 25568667, 2014). "Few reports have been published that describe the impact of RGS16 on cancer cell signaling and progression." (PMID 25568667, 2014). "Nevertheless, despite its well-established roles in various cancers, the function of RGS16 in GC, especially its involvement in ferroptosis regulation, remains largely unknown." (PMID 40413527, 2025). "Besides, numerous studies have shown that RGS16 can act as a biomarker for cancer diagnosis and prognosis." (PMID 40413527, 2025). "It has been reported that RGS16 correlates with the malignant progression of various cancers." (PMID 40413527, 2025). "Moreover, many studies have shown that RGS16 can be used as a biomarker for cancer diagnosis and prognosis." (PMID 38363937, 2024). "RGS16 exerts different biological functions in a variety of benign and malignant tumors." (PMID 32319728, 2020). "The 8-mRNAsi based prognostic model in our signatures includes RGS16, LYVE1, hnRNPC, ANP32A, AIMP1, ZNF66, PIK3R3, and MAP2K7, in which several genes have been reported to be linked with stemness features or be involved in cancer progression." (PMID 33329703, 2020). "To date, this is the first report demonstrating RGS16 induced inhibition of cancer cell invasion." (PMID 25568667, 2014). "Recently, evidence has demonstrated a role of RGS16 in cancer signaling." (PMID 25568667, 2014). "RGS16 protein is expressed in a variety of tissues and is associated with a variety of cancers, but the application of RGS16 in the field of cancer is not perfect, and most of the current studies believe that RGS16 can be used as a biomarker for the diagnosis and prognosis of a variety of cancers." (PMID 38363937, 2024). "Thus, monitoring Rgs16 expression might lead to the identification of receptors and ligands important in stem cell function and cancer initiation." (PMID 26438693, 2015).
cancer (continued). "Our results suggest that PAR4 activation contributes to cancer progression, which is attenuated in the presence of RGS2, RGS4, and RGS16." (PMID 32517689, 2020). "This is the first report of regulation of RGS16 by pRb and RGS16-mediated inhibition of EGF-induced migration and invasion in normal and cancer cells." (PMID 25568667, 2014). "Since BET bromodomain proteins are readers of histone acetylation, we assayed JQ1, a selective inhibitor of BET with efficacy against a number of different cancers, but it did not induce Rgs16::GFP in cultured primary PDA cells (5% FBS)." (PMID 33244070, 2020). "Furthermore, PAR4 activation promoted cell proliferation and cancer-related gene expression, which were attenuated by RGS2, RGS4, and RGS16." (PMID 32517689, 2020). "Additionally, we have previously shown that orthotopic transplantation of primary cancer cells isolated from KIC;Rgs16::GFP PDA tumors regrow GFP-positive PDA specifically in duct-like structures in recipient NOD-SCID mice." (PMID 33244070, 2020). "Finally, PAR4-mediated HT29 cancer cell progression was significantly inhibited by RGS2, RGS4 and RGS16, as determined based on PAR4-activated cell proliferation and expression patterns of cancer progression-related genes." (PMID 32517689, 2020). "Altogether, our data show that ORF3 mediates an antitumoral effect in vivo, most likely by inducing apoptosis of cancer cells through mechanisms independent of the expression of RGS16 in the host tissues." (PMID 30526524, 2018). "Therefore, RGS16 may affect the prognosis of patients by regulating the activity of immune cells and has no direct impact on the activity and apoptosis rate of cancer cells." (PMID 36925652, 2023). "Rgs16 expression in mouse PDA tumors and primary cancer cells in culture is inducible, not constitutive, in cells that express oncogenic Kras." (PMID 33244070, 2020).
metabolic disease (4 papers, 2019 to 2022). A congenital disorder (due to inherited enzyme abnormality) or acquired (due to failure of a metabolically important organ) disorder resulting from an abnormal metabolic process. "Interestingly, when compared to Viv chow, both SO + CO and PL + CO diets caused dysregulation of 8 to 22 genes associated with metabolic disease, whereas the CO diet yielded only 2 disease-related genes (Atp2a1 and Rgs16), both of which are linked to inflammation." (PMID 31912136, 2020). "Therefore, the present review summarizes the structure, characteristics, regulatory mechanisms and known functions of RGS16 in different diseases such as immunity, inflammation, tumors and metabolic disorders." (PMID 36120550, 2022).
infection (2 papers, 2016 to 2023). The state of being infected such as from the introduction of a foreign agent such as serum, vaccine, antigenic substance or organism. "Eight days after infection, both LCMV strains showed increased expression of genes associated with CD8+ T cell activation, such as Pdcd1, Rgs16 and Lag3, in agreement with previous findings." (PMID 37813964, 2023). "Genes involved in the control of cell migration were also represented in the HP1 list (e.g. Ccr2, Ccr5, Itga1, Itgb1, Gpr183, Rgs16), with some having an essential role in the recruitment of CD8 T cells in the lung following infection by a pathogen." (PMID 27883012, 2016).
inflammation (1 paper, 2022). Aberrant reaction of the microcirculation characterized by movement of fluid and leukocytes from the blood into extravascular tissues. "Circadian-induced expression of G0/G1 switch 2 and RGS16 in hepatocytes, which regulates substrate oxidation in resting hepatocytes, has recently been reported to reduce liver inflammation and fibrosis in obese mice, suggesting that RGS16 is essential for maintaining liver health." (PMID 36120550, 2022).
mental illnesses (1 paper, 2019). "These miRNAs and mRNAs were previously implicated in psychiatric disorders (miR-320a and SP4), key processes of the central nervous system (CAPNS1, RGS16, SP4) or pathways involved in mental illnesses (miR-155-3p)." (PMID 31801218, 2019).
RGS16 also shares sentences with these, for which no sentence is quoted: colon cancer (2 papers); Glucose intolerance (2); lymph node metastasis (2); viral infection (2); Acidosis (1); acute myeloid leukemia (1); COVID-19 (1); diffuse large B-cell lymphoma (1); enteroviral infections (1); follicular lymphoma (1); hematologic malignancies (1); injury (1); insulinoma (1); pancreatic ductal adenocarcinoma (1); prostate carcinoma (1); psoriasis (1); retinoblastoma (1); sleep disorder (1); triple-negative breast carcinoma (1).